GLP1R (glucagon like peptide 1 receptor)
Diseases named in the same sentence as GLP1R in open-access papers (continued):
Sharing a sentence is not in itself a finding about the gene and the disease.
Obesity (continued). "As dual-agonism may provide superior glucoregulatory and anti-obesity effects to mono-agonists, there have been attempts to modify the peptide sequence of OXM for more balanced dual agonism for GLP-1R and GCGR." (PMID 37514148, 2023). "Our data support that exposure to the obesogenic environment, without the development or manifestation of obesity, is sufficient to alter the response to GLP1R agonists." (PMID 37293487, 2023). "GLP-1R, 5-HT2CR and MC4R agonists have been developed for human obesity treatment." (PMID 36592795, 2023). "Exposure to a CAF diet during the early stages of obesity reduces the effects of peripheral and central GLP1R agonists, and WAT does not express a functional GLP1 receptor." (PMID 37293487, 2023). "Despite reports of positive outcomes from simultaneous agonism of both GLP-1R and Y2-R, this approach alone has not generated the same clinical benefits as obesity surgery." (PMID 37308546, 2023). "The incretin receptors, glucagon-like peptide-1 receptor (GLP-1R) and glucose-dependent insulinotropic polypeptide receptor (GIPR), are prime therapeutic targets for the treatment of type 2 diabetes (T2D) and obesity." (PMID 36774542, 2023). "The GLP-1R agonists are in the first line of treatment for T2DM and obesity." (PMID 36145148, 2022). "In murine models of T2DM and obesity, GLP-1-Fc-FGF21 D1 improved liver function, serum and hepatic lipid profiles, and reduced body weight and NAS scores with an efficacy superior to either FGF21 or GLP1R agonists alone." (PMID 35203484, 2022). "Liraglutide, a commonly used GLP-1R agonist in clinical practice, is also being investigated to treat NAFLD, a condition that is common in those with obesity and T2DM and is increasing in incidence and for which drug development is challenging and few effective therapies are available." (PMID 36311486, 2022). "Liraglutide is a GLP-1R agonist used for the treatment of T2DM and obesity." (PMID 36077491, 2022). "Furthermore, a balanced unimolecular GLP‐1R and GIPR agonist reduced bodyweight, food intake, and fat mass in mice with diet‐induced obesity to a greater extent than liraglutide." (PMID 34713962, 2022). "Because improving glucose control with antidiabetic therapies appears to restore the insulinotropic effect of GIP in patients with T2D, growing evidence suggests that GLP-1R/GIP-R co-agonists could represent a promising strategy for treating T2D and obesity." (PMID 33671882, 2021). "Therefore, dual agonism of GLP-1R, which exerts glycaemic control, and GIPR represents a strategy in treating obesity and T2DM." (PMID 34072172, 2021). "Detailed mechanistic research is also needed to establish the relative contributions of G protein- and β-arrestin-mediated effects at both GLP-1R and GCGR and will help clarify how investigational incretin receptor agonists are prioritised during drug development for T2D and obesity." (PMID 33933675, 2021). "Due to these beneficial effects of GLP-1R activation on metabolism, several drugs have been developed that act on the GLP-1 receptors, including the GLP-1RAs liraglutide, dulaglutide and exendin-4, used in the treatment of T2DM and obesity." (PMID 30863364, 2019). "These important negative data support the hypothesis that even in a weight-reduced state from peak obesity, the DVC GLP-1R and amylin receptors theoretically remain as continued viable drug targets for sustaining weight loss." (PMID 31186439, 2019). "GLP-1 receptor (GLP-1R) agonist has shown benefits on kidney diseases, but its direct role on kidney metabolism in obesity is still not clear." (PMID 29590132, 2018). "Recent study further reported that GLP-1R agonist Ex-4 inhibited renal cholesterol accumulation and inflammation in diabetic apoE knockout mice.However, the direct role of GLP-1R agonist on renal metabolic abnormalities in obesity remains not clear." (PMID 29590132, 2018).
Obesity (continued). "Hence, subchronic d-allulose treatment at early LP ameliorates LP-specific hyperphagia, obesity, adiposity and IGT in HFD-fed mice via GLP-1R signaling." (PMID 29317623, 2018). "In addition to GLP-1R/GCGR dual agonists, a chimeric peptide as dual GLP-1/GIP receptor agonists has been developed, showing enhanced therapeutic potential for obesity and related comorbidities." (PMID 30459715, 2018). "Several exogenous GLP-1 receptor (GLP-1R) agonists have been approved as therapies for T2D, including exenatide, liraglutide, dulaglutide, and albiglutide; liraglutide has also been approved for the treatment of obesity." (PMID 27093610, 2016). "We found that GLP-1R was expressed in the rat kidney and importantly, its expression was not altered by maternal obesity, diet-induced obesity or Exendin-4 treatment." (PMID 27004609, 2016). "Further investigations are required to expand our knowledge on this class of non-peptidic GLP-1R agonists aiming at pharmacotherapies for obesity and related metabolic diseases." (PMID 21151924, 2010). "Incretin-based therapies, particularly glucagon-like peptide-1 receptor agonists (GLP-1 RAs), have emerged as potentially promising therapeutic agents for improving ovarian function, especially in women with polycystic ovary syndrome (PCOS) and obesity-related reproductive dysfunction." (PMID 42278283, 2026). "Importantly, both strategies have been translated into efficacious obesity pharmacotherapies when combined with GLP‐1R agonism; tirzepatide, a marketed GIPR/GLP‐1R dual agonist and maridebart cafraglutide, a GIPR antagonist/GLP‐1R agonist currently in phase III clinical trials." (PMID 41287212, 2026). "Furthermore, native GIP infusion alone fails to reduce food intake in patients with obesity nor does it drive additional reduction in energy intake when paired with the GLP-1R agonist liraglutide." (PMID 40507574, 2025). "Indeed, GLP-1R knockout mice do not develop obesity although postembryonic deletion of GLP-1Rs in the paraventricular nucleus of the hypothalamus (PVH) leads to weight gain due to increased food intake." (PMID 39644359, 2025). "The human POMC cluster C4-374, corresponding to the mouse Glp1r-expressing POMC neurons, instead expresses the calcitonin receptor (CALCR), highlighting the interspecies heterogeneity of POMC populations, which has direct implications for currently licensed obesity therapies." (PMID 39910307, 2025). "Recent studies have shown that glucagon-like peptide-1 receptor agonists (GLP-1RA), an anti-diabetes and anti-obesity drug class, have a beneficial impact on cardiovascular outcomes in patients with metabolic disorders such as obesity and type II diabetes mellitus." (PMID 40919598, 2025). "Glucagon-like peptide 1 receptor agonists (GLP-1 RAs), the natural homologs of the incretin hormone GLP-1, have been approved for weight management; 2.4 milligrams (mg) of semaglutide once weekly or 3.0 mg of liraglutide once daily is effective in treating obesity." (PMID 41451292, 2025). "Unimolecular GLP1R/GIPR dual agonists not only amplify the metabolic benefits of GLP-1 therapies but may also reduce common side effects, offering an effective strategy for managing obesity and T2D-related conditions." (PMID 40166681, 2025). "Additionally, glucagon-like peptide 1 receptor agonists (GLP-1 RAs) may also reduce weight and prevent T2DM in patients with obesity." (PMID 40725640, 2025). "Based on the link between obesity and AEH/EC, we hypothesized that the combination of a GLP-1R agonist and levonorgestrel would be useful as a novel treatment or prevention regimen and tested this hypothesis in preclinical models using EC cell lines and patient-derived organoids." (PMID 40002193, 2025). "Our analysis does not account for the recent, increasing use of glucagon-like peptide-1 receptor agonist medications for weight management, but this use may have started to influence neighborhood obesity rates." (PMID 41026491, 2025).
Obesity (continued). "A cadaveric study found a decrease in GLP-1R expression in the LH that correlated with increased BMI, suggesting that reduced GLP-1R signaling in the LH may contribute to dysregulated feeding behavior in individuals with obesity." (PMID 40722684, 2025). "Regardless, dual agonists targeting both GLP1R and GIPR decrease body weight and improve glucose tolerance in animal models of obesity and T2D in mice, non-human primates and obese patients with and without T2D [5,] with greater efficacy than GLP1R agonism alone." (PMID 38653401, 2024). "Currently, there are other dual GIPR/GLP-1R agonists available, such as GLP-1R/GR (glucagon receptor), GLP-1R/AR (amylin receptor), and GLP-1R/NPYR (peptide YY binds to neuropeptide Y receptors) and even triple agonists that can activate GIPR to treat obesity and T2DM." (PMID 38987789, 2024). "Interestingly, monomeric GLP-1R agonists, like semaglutide and liraglutide, as well as dual GLP-1R agonists like tirzepatide, have been FDA-approved for the treatment of T2DM and metabolic disorders, including chronic weight management in adults with obesity." (PMID 38612620, 2024). "Regarding future obesity treatment strategies implementing novel GIP/GPL-1 co-agonists that are emerging it is unclear whether every co-agonist will be as beneficial as and superior to single GLP-1R agonism." (PMID 37592302, 2023). "Another study has shown that GLP-1/GLP-1R signaling in macrophages suppresses M1 polarization and triggers M2 polarization.In light of these findings, we speculate that GLP-1 alleviates obesity-related inflammation via inhibiting macrophage recruitment and promoting M2 macrophage polarization in AT." (PMID 37283763, 2023). "Meanwhile, research on the mechanism and efficacy of GLP-1R/GIPR dual agonists and GLP-1R/GIPR/GCGR triple agonists paves the way to a ground-breaking therapy specific for obesity, which suggests multi-target drugs may have more advantages than a single target." (PMID 36843578, 2023). "The issue of obesity and insulin resistance prompted the design of a number of studies investigating the effects of antidiabetic drugs in PCOS, as reported in recent and very exhaustive reviews on the available clinical trials on glucagon-like peptide 1 receptor agonists (GLP-1RA) in PCOS." (PMID 37093453, 2023). "Thus “triple agonism” of GLP-1R, GIPR, and GcgR could represent a new standard for pharmaceutical intervention in obesity." (PMID 35809773, 2022). "However, recent clinical trials with advanced therapeutic candidates including glucagon-like peptide 1 receptor (GLP1R) agonism are promoting the belief that breakthrough, drug-based management of obesity may be possible." (PMID 34815532, 2022). "Interestingly, the role of GLP1‐RAs may not be confined to the management of hypogonadism in patients with DM and/or obesity, because the GLP1/GLP1R axis seems to influence sperm metabolism." (PMID 33818920, 2021). "It has been demonstrated that GLP-1R/NPY2R dual agonists in vivo exert anorectic effects along with the ability to reduce blood glucose levels, thereby confirming that they could act as promising anti-obesity and antihyperglycemic agents." (PMID 34443409, 2021). "Interestingly, glucagon-like peptide-1 receptor agonists (GLP-1RAs), used in the treatment of T2DM and obesity, are known to show pro-cognitive and neuroprotective properties, and exert modulatory effects on immune, endocrine and metabolic processes in the central nervous system." (PMID 34003475, 2021). "In this context, we advocate for a pragmatic approach to select the most suitable partnering incretin, possibly a dual GLP-1R/GIPR agonist such as NNCOO90-2746, to achieve the appropriate therapeutic outcome for the long-term management of metabolic diseases like T2D and obesity." (PMID 33349332, 2020).
Obesity (continued). "Since the GLP-1R and NPY2R differ with respect to their tissue distribution and signaling properties, a dual agonist peptide such as EP45 might constitute an ideal medicinal agent with which to simultaneously treat T2DM and obesity." (PMID 29491394, 2018). "Therefore, we suggest that GLP-1R agonists via BAT activation reduce both hyperlipidaemia and hyperglycaemia, and possibly even atherosclerosis, in addition to the effects of BAT activation on obesity." (PMID 26254578, 2015). "Furthermore, several RCTs in adults with overweight or obesity have evaluated other multi-receptor drugs, such as Retatrutide, which targets GIPR/Glucagon receptor (GCGR)/GLP-1R, and Mazdutide, which targets GCGR/GLP-1R, showing promising results in both glycemic management and weight reduction." (PMID 39968298, 2025). "Thus, with continuing development on GIP/GLP-1R co-agonists modalities, it is hoped that clarity can be ascertained as to whether GIPR agonism or antagonism has the greatest role to play in management of obesity and related metabolic diseases." (PMID 38861364, 2024). "In comparison to the dopaminergic machinery, GLP1R is not substantially expressed in the visceral adipose tissue of obese patients and its expression was also not significantly altered in the adipose tissue of these patients with obesity at distinct degrees of dysmetabolism." (PMID 36768789, 2023). "Moreover, the anti-obesity effect was absent in GLP-1 receptor null (GLP-1R KO) mice and in mice that received daily intraperitoneal injections of a PYY receptor antagonist, confirming the causal relationship between GLP-1 and PYY on reduction of body fat accumulation and glucose homeostasis." (PMID 32500037, 2020). "Non-peptidic GLP-1R agonists represent a promising class of therapeutic agents for T2DM and obesity, offering the potential advantages of oral bioavailability and convenient dosing over traditional peptide-based GLP-1R agonists." (PMID 41303737, 2025). "The analogues of this hormone, the glucagon-like peptide-1 receptor agonists (GLP-1RAs), are widely used in the treatment of T2DM and obesity, and their beneficial role in cardiovascular effects has now been established." (PMID 41367443, 2025). "It is in line with multiple prior studies demonstrating that endogenous GLP-1 is not critical for regulating food intake, and that GLP-1R–KO mice and mice treated with GLP-1R antagonists are also protected from obesity." (PMID 40857106, 2025). "In this study, terazosin demonstrated beneficial effects on hyperglycemia, obesity, and NAFPD by activating GPR119 rather than acting as a GLP‐1R or analog." (PMID 39413003, 2025). "The emergence of glucagon-like peptide-1 receptor agonists (GLP-1 RAs; semaglutide and others) now promises effective, non-invasive treatment of obesity for individuals with and without diabetes." (PMID 38002464, 2023). "Others have demonstrated that the positive outcomes of obesity surgery (i.e., changes in body weight and improved glucose homeostasis) are sustained in mice in the absence of GLP-1R or Y2-R, or both GLP-1R and Y2-R66,67." (PMID 37308546, 2023). "Some glucagon-like peptide-1 receptor agonists (GLP-1 RAs), first used in the treatment of type 2 diabetes mellitus (T2DM), have been approved for the treatment of obesity in patients with or without T2DM (liraglutide—LIR, semaglutide—SEM, and tirzepatide—TIR)." (PMID 38791086, 2024). "Finally, Liraglutide, a glucagon-like peptide-1 receptor agonist, though not formally studied for treatment of obesity in patients with cirrhosis, does not need dose adjustment, and could be a useful tool to treat obesity in patients with cirrhosis, but more evidence is needed." (PMID 31652761, 2019).
Hyperglycemia (205 papers, 2011 to 2026). An increased concentration of glucose in the blood. "As some examples, the use of metformin and glucagon-like peptide 1 receptor agonists was associated with better prognosis while administered to treat hyperglycemia in hospitalized patients with COVID-19." (PMID 38243977, 2024). "The upregulation of SUCNR1 associated with hyperglycemia differs, however, from the downregulation reported for GLP-1R in conditions associated with high glucose." (PMID 38713514, 2024). "Butyricimonas has been reported to improve hyperglycemia through the regulation of GLP-1R in mice fed a high-fat diet and to be associated with lipid metabolism." (PMID 36982979, 2023). "The current study discovered that liraglutide influenced the adrenal gland before entering the brain in diabetic rats, indicating that hyperglycemia caused a change in GLP-1R sensitivity." (PMID 35890201, 2022). "The same group further assessed various ratios of GCGR to GLP-1R potency of their peptides, on the extent of weight loss while minimising hyperglycaemia." (PMID 34566894, 2021). "As a result, GLP-1 receptor (GLP-1R) agonists (GLP-1RA) reduce hyperglycemia with little risk of hypoglycemic episodes." (PMID 31443356, 2019). "The GLP-1R agonist exendin-4 is potent in ameliorating hyperglycemia and at the same time has lower risk of causing hypoglycemia." (PMID 28122026, 2017). "GLP-1R agonists have been used in clinical for the treatment of T2D, hyperglycemia is one of the leading risk factors for ischemic cerebrovascular diseases." (PMID 26863436, 2016). "STZ treated SPD rats with T1DM exhibit insulinopenia, rapid body mass loss, and acute severe hyperglycemia along with reduced gastric GLP-1R expression." (PMID 25893200, 2015). "Importantly, hyperglycemia-induced peripheral chemoreflex sensitization and associated basal sympathetic overactivity were abolished by GLP1R activation in the CB suggesting a role in a homeostatic response to high blood glucose." (PMID 35100822, 2022). "A recent report showed that chronic hyperglycemia could lead to the loss of the glucagon-like peptide-1 receptor (GLP-1R) from the cell surface and impairment of GLP-1R signaling." (PMID 35058775, 2021). "Therefore, concurrent agonism at the GLP-1R and GCGR is important for the glucose-lowering effect of OXM: GLP-1R activation offsets the hyperglycaemia associated with GCGR activation." (PMID 34566894, 2021). "“Diabetic conditions” – such as hyperglycemia and hyperlipidemia – can lead to the loss of the GLP-1 receptor (GLP-1R) from the cell surface and, thereby, impair GLP-1 signaling, which may underlie the reduced clinical efficacy of GLP-1R activators." (PMID 27777568, 2016). "Because hyperglycemia is one of the leading risk factors for ischemic cerebrovascular diseases, it provided a potential clinical use of GLP-1R agonists for the treatment of stroke in T2D patients or individuals at high risk to suffer from a stroke (e.g. pretreatment strategies)." (PMID 26863436, 2016). "We posit that any hypothetical impairment of Betulinic Acid conjugates by hyperglycemia can be averted by combining BA with newer glucagon-like peptide-1 receptor (GLP-1R) agonists." (PMID 40565062, 2025). "Another study reported that chronic hyperglycemia, mimicking T2D, induced the GLP-1R to switch from Gαs to Gαq as the proximal step leading to increased insulin secretion." (PMID 40526441, 2025). "Background/Objectives: Glucagon-like peptide-1 receptor agonists are increasingly used worldwide for weight and hyperglycemia management." (PMID 40150111, 2025). "More recently, the idea of a Gαs-Gαq switch has been proposed, describing how the GLP-1R adapts to chronic hyperglycemia by preferentially coupling to Gαq to support insulin secretion." (PMID 40526441, 2025). "LB-A represents a novel small molecule agonist that ameliorates hyperglycemia in diabetic mice through specific activation of the GLP-1R/cAMP/PKA/pCREB/PTEN/FOXO1 pathway." (PMID 41373699, 2025).